CD14 (CD14 molecule)
Diseases named in the same sentence as CD14 in open-access papers (continued):
Sharing a sentence is not in itself a finding about the gene and the disease.
melanoma (continued). "Therefore, monocytes from melanoma progressively acquire a CD14+/HLA-DR-/low suppressive phenotype that alters T-cell proliferation and interferon-γ production while enhancing the secretion of inhibitory cytokines such as IL-6, TNF-α and TGF-β within the tumor milieu." (PMID 29755693, 2018). "Interestingly, also BDCA1+ DCs cultured with serum of melanoma patients started co-expressing CD14." (PMID 30235890, 2018). "Interestingly, melanoma patients that were vaccinated with DC vaccines with a content of more than 25% BDCA1+CD14+ cells showed a reduced T-cell response to the immunomonitoring molecule Keyhole Limpet Hemocyanin (KLH) compared to patients whose DC vaccines contained less than 25% BDCA1+CD14+ cells." (PMID 30235890, 2018). "Elevated CD14+ DC3 counts correlate with decreased survival in non-small cell lung cancer and reduced survival rates in melanoma." (PMID 40584260, 2025). "To answer these questions, we set out to characterize CD1c+CD14+ cells in NSCLC and investigate their development in the context of melanoma and NSCLC." (PMID 38242119, 2024). "We postulate that the classical CD16− monocytes are recruited into the melanoma TME, likely via tumour-derived CCL2, where they upregulate CD163 and gradually lose the expression of CD14 and CCR2." (PMID 38903497, 2024). "Analysis of correlation between CD1c+CD14+ frequencies and progression-free survival (PFS) for responding melanoma patients showed that high CD1c+CD14+ frequencies in the vaccine correlate with shorter PFS (R2 = 0.9570, p = 0.0038, n = 5)." (PMID 38242119, 2024). "At present, a number of studies have reported that CD14+ or CD68+ macrophages have been observed to up-regulate the expression of PD-L1 in a variety of cancer tissues, including hepatocellular carcinoma, melanoma and ovarian cancer." (PMID 39003253, 2024). "We first determined the balance between CD1c+CD14− cells and CD1c+CD14+ cells in peripheral blood of early-stage NSCLC and stage III and IV melanoma patients by flow cytometry and compared this with healthy donors (HDs)." (PMID 38242119, 2024). "PD-L1+ CD14+ monocytes in peripheral blood are correlated with shorter survival in patients treated with anti-PD-1 antibodies, including NSCLC, gastric cancer, melanoma, parotid cancer, and bladder cancer." (PMID 36013407, 2022). "In melanoma and primary glioma, the blockade of STAT3 and p38 MAPK signaling pathways promoted the differentiation of CD14+ myeloid cells to CD1a+." (PMID 36230990, 2022). "Then, we determined their cellular origin (melanoma cells or immune cells, as T and B lymphocytes, monocytes and dendritic cells) by measuring the percentage of EVs positive for CD146, CD8, CD19, CD14 and CD1a, respectively." (PMID 35042524, 2022). "For example, an increased frequency of circulating CD14+CD16−HLA-DRhi monocytes prior to treatment, along with a decreased frequency of T cells, correlate with survival and response to anti-PD-1 in melanoma patients." (PMID 36130508, 2022). "BOK and CYLD were down-regulated, and CD14 and FASLG were up-regulated in melanoma samples, which were in accordance with the bioinformatics results." (PMID 35387121, 2022). "In mice with YUMMER 1.7 melanoma, we observed increased frequencies of Tim-3+PD-1+ CD8+ TILs as well as PS+, CD11c+, and CD14+ PD-1+Tim-3+ CD8+ TILs over time." (PMID 35316223, 2022). "To evaluate the relationship among PON3, CD14 and RAP1B and prognoses of melanoma patients, we conducted Kaplan–Meier survival analysis according to gene expression data of PM." (PMID 34439311, 2021). "By proteomics we identified five proteins in plasma CD81sEV that were differentially expressed between HD and stage II (APOA5, PON1, PON3 and CD14) and between HD and stage III–IV, advanced stage melanoma, (RAP1B)." (PMID 34439311, 2021).
melanoma (continued). "In metastases from melanoma patients, high levels of miR-146a, miR-155, miR-125b, miR-100, let7e, miR-125a, miR-146b, and miR-99b were detected and correlated with CD163, CD14, CD209, CD68, ITGAM, and CD33 myeloid markers." (PMID 32793228, 2020). "In another trial with melanoma patients, BDCA1+CD14+ cells were shown to inhibit T cell proliferation in an antigen-dependent fashion resulting in impaired responses to monocyte-derived DCs." (PMID 31191529, 2019). "CD14+ monocytes were isolated from peripheral blood buffy coats and cultured in TCM derived from the human melanoma cell line WM115." (PMID 30232321, 2018). "Consistent with a previous study on melanoma patients, we detected variable level of CD80, CD83 and/or CD86 expression on CD14+HLA-DR−/low MDSC in the PB and/or ascites from OC; however, their functional significance remains elusive." (PMID 29100353, 2017). "Consistently, CD14 and CSF1R expression was higher in MITFlow/c-JUNhigh melanomas, indicating increased numbers of myeloid cells." (PMID 26530832, 2015). "Immunohistochemical analysis of representative cases from this cohort confirmed that MITFlow/c-JUNhigh melanomas were dedifferentiated (gp100−) and infiltrated by CD45+ immune cells that were largely CD14+ myeloid cells." (PMID 26530832, 2015). "The greatest numbers of infiltrating immune cells were macrophages (CD14+ cells), while CD3+ T cells were scarcely represented within the analyzed primary melanomas (4.3%)." (PMID 23189169, 2012). "For each expected cell type in each region, we selected its marker genes from existing literature, which included PMEL for malignant cells in melanoma regions, COL1A1 for fibroblast in stroma regions, MS4A1 for B cells and CD14 for macrophage in lymphoid tissues." (PMID 39402626, 2024). "In addition—following the in vitro reconstitution of a human melanoma TME using tumor lines (BLM, Mel624 or A375)—PGE2 and IL-6 produced by the tumor transform cDC2s into CD14+ DCs, characterized by an immunosuppressive phenotype." (PMID 37190135, 2023). "Indeed, tumor-infiltrated CD14+ cDCs express higher levels of TAM-related markers such as CD206, MerTK, and CD163 compared with blood-circulating CD14+ cDCs in melanoma patients." (PMID 35454882, 2022). "Total CD14+ cMo frequencies are predictive of anti-PD-1 responses in melanoma patients, but we did not observe this in our cohorts of NSCLC patients." (PMID 35493454, 2022). "Intra-tumoral CD56+ NK cells, CD14+CD16++ non-classical monocytes, and CD68+CD14+ macrophages have been positively correlated with ipilimumab response in melanoma patients." (PMID 35326731, 2022). "Our results suggested that TNF receptors, MHC molecules, ITGAM, CD247 or CD14 leading gene sets can preciously distinguish the responders for non-responders in patients with melanoma that received ICB therapies." (PMID 34238310, 2021). "CD14+HLA-DR−/low MDSCs isolated from melanoma patients inhibit T cells via TGF-β with no involvement of ARG1 and iNOS." (PMID 32793192, 2020). "Moreover, IFNγ signatures (CXCL10, CXCL9, IDO1, IFNG, and STAT1) and myeloid lineage phenotypic and functional markers (CD14, CD163, CD33, and CD68) were also significantly increased in melanoma patients with high ETV7." (PMID 33424867, 2020). "As observed in patients undergoing M-ILP, the melphalan-exposed melanoma cells also triggered an increased proportion of CD33+CD14+CD16++ non-classical monocytes in vitro." (PMID 30560089, 2018). "Tumor-conditioned medium (TCM) obtained from the human SK-MEL melanoma cell line did not affect the ability of human DCs generated from CD14+ monocytes to stimulate allogeneic T cells." (PMID 29242535, 2017). "Interestingly, FACS analysis showed that, upon stimulation with melanoma-derived factors, CD30 was selectively upregulated in the CD14+DR− monocyte population, a cell subset known as monocytic myeloid-derived suppressor cells (MDSCs)." (PMID 27983661, 2016).
melanoma (continued). "Previous work identified CD14+HLA-DRlo/neg monocytes as a predictor of poor prognosis and powerful mediators of immune suppression in GBM, NHL, chronic lymphocytic leukemia melanoma, and renal cell cancer." (PMID 25512872, 2013). "After three passages, the cells isolated from the melanomas by collagenase digestion consisted almost entirely of spindle-shaped, fibroblastic mononuclear cells, which did not stain for CD14, CD68, VNR, TRAP, HMB-45 and S100." (PMID 16641914, 2006). "Dissecting the molecular properties of tumor-conditioned CD14+ cells, a panel of specific miRNAs was found to associate with the immunosuppressive and pro-inflammatory functions of MDSCs and to predict resistance to ICPi, but not TKI in melanoma patients." (PMID 37347257, 2023). "Although the detailed characteristics are not known, microvesicles isolated from plasma of advanced melanoma patients, but not from healthy donors were shown to address CD14+ monocytes, resulting in CD14+ suppressed T-cell functions (possible with downregulation of HLA-DR)." (PMID 35477770, 2022). "Although we found an association between CD68+ macrophages and high PDCD4 expression using QIF, PDCD4 was not present at high levels in the macrophage (defined as CD14+/C1QA−) or microglia (defined as C1QA+) populations in our one sequenced melanoma brain metastasis sample." (PMID 33801444, 2021). "Moreover, IFN-α priming may also have a “mobilizing” activity on DC precursors: it was recently reported that 1–3 MU subcutaneous IFN-α enhances the proportion of circulating CD14+ and CD14 + CD16+ monocytes in both healthy donors and melanoma patients." (PMID 25053129, 2014). "Moreover, IFN-α priming may also have a “mobilizing” activity on DC precursors: it was recently been reported that 1–3 MU subcutaneous IFN-α enhances the proportion of circulating CD14+ and CD14 + CD16+ monocytes in both healthy donors and melanoma patients." (PMID 25053129, 2014). "The percentage of CD14+ cells isolated from apheresis products, purity of isolated CD14+ cells, efficiency of CD14+ cell selection as well as viability and yield of IDCs were indistinguishable between melanoma patients and normal volunteer blood donors used as control." (PMID 16911798, 2006). "Three different DC lines cultured for 7–9 days in medium containing GM-CSF and IL-4 (CD14−, CD36+ and CD83−) showed higher levels of intracellular MC1R than short time cultured monocytes, comparable to that observed in the low MC1R expressing BL melanoma cell line." (PMID 12177778, 2002). "To explore whether the identified proteins, APOA5, PON1, PON3, CD14 and RAP1B, could be of any clinical relevance, we evaluated their expression in silico in relation to the available clinical information in the TCGA dataset of primary melanoma samples (PM, n = 80)." (PMID 34439311, 2021). "Utilizing melanoma and NSCLC cell lines we show that CD1c+CD14+ cells emerge from cDC2s but not monocytes, through IL-6 and macrophage colony-stimulating factor (M-CSF/CSF1) secreted by tumor cells." (PMID 38242119, 2024). "CD14, ITGAM, CD247 and MHC molecules not only significantly dysregulated between the responders and non-responders of patients with melanoma but also presented accuracy prediction of immunotherapy response." (PMID 34238310, 2021). "Further analysis revealed that BDCA1+CD14+ cells were not only present in peripheral blood of stage III and stage IV melanoma patients, but that metastatic lesions in the skin, lymph nodes, and colon also showed increased frequencies of these cells." (PMID 30235890, 2018). "Of note, treatment with scFvFITC:sFasL induced significant apoptosis in 3 out of 3 primary patient-derived melanoma cells pretargeted with anti-MCSP-FITC, whereas no significant increase in apoptosis was observed in cells pretargeted with anti-CD14-FITC." (PMID 29038485, 2017).
melanoma (continued). "Similar to ovarian cancer, VLC isolated from melanoma, breast, lung, or endometrial cancer expressed endothelial markers such as CD146 and CD31, and myeloid markers such as CD14 (data not shown)." (PMID 19545375, 2009). "After incubation for 24 h on glass coverslips, the cells isolated from the metastatic melanomas, when cultured in the presence and absence of M-CSF and RANKL, strongly expressed the monocyte/macrophage marker CD14, which is not expressed by osteoclasts." (PMID 16641914, 2006). "In a study assessing melanoma and NSCLC, both tumors with high immune infiltration, researchers found that non-mature CD1c+ CD14- cDC2s could be directed towards DC3s (CD1c+ CD14+ cDC2s) through tumor-derived IL-6 and M-CSF (CSF1)." (PMID 40584260, 2025). "Moreover, when the melphalan-treated melanoma cells were co-cultured with PBMCs, this triggered an increased proportion of CD33+CD14+CD16++ non-classical monocytes among the PBMCs." (PMID 30560089, 2018).
atherosclerosis (108 papers, 2008 to 2025). A disease characterized by the build-up of fatty material and calcium deposition in the arterial wall resulting in partial or complete occlusion of the arterial lumen. "The intermediate CD14++CD16+ monocytes have been directly associated both with the atherosclerosis burden as well as with the occurrence of adverse atherosclerotic cardiovascular events in patients without and with CKD." (PMID 39273110, 2024). "It should be noted that both DM and hypertension increase the risk of and can contribute to atherosclerosis, and CD14+CD16+ monocytes are major effectors of HIV-associated atherosclerosis." (PMID 39253970, 2024). "TREML4 was upregulated in HD in both CD14 clusters and expression on monocytes has been associated with inflammation and increased risk for atherosclerosis." (PMID 37361874, 2023). "Our previous studies have examined smoking-associated methylation effects in purified CD14+ monocytes and observed associations with atherosclerosis markers or upregulation of transcription via enhancer activation." (PMID 37231515, 2023). "A greater number of miRNAs had altered expression in CD16+ monocytes, compared to CD14+ monocytes and Ingenuity pathway analysis linked a number of these miRNAs with atherosclerosis-related genes." (PMID 32582174, 2020). "CD14+CD16++ monocytes have proinflammatory activity that is associated with an increased risk of atherosclerosis and CVD." (PMID 32850849, 2020). "Atherosclerosis-associated monocytes/macrophages showed high expressions of Adgre1, Cd14, Fcgr1, and Csf1r and a low expression of Ly6c2." (PMID 33013913, 2020). "Conversely, reduced expression of miR27a-3p in CD14+ monocytes was associated with the presence of early atherosclerosis, which paralleled the increase in IL-8, MCP-1, VEGF, and TF." (PMID 32188016, 2020). "Decreased expression of CDKN2A/2B/2BAS in leukocytes associates with increased CC-IMT atherosclerosis surrogate marker and proatherogenic CD14++CD16+ monocytes in T1DM patients." (PMID 31299986, 2019). "Here we present the CD14+ blood monocyte transcriptome and epigenome signatures associated with human atherosclerosis." (PMID 28855511, 2017). "We found the CD14 C-260T T-allele in 56% of the cohort and evidence of subclinical atherosclerosis in 27%." (PMID 25622527, 2015). "CD14 has furthermore been associated with the development of atherosclerosis and the recurrence of vascular events." (PMID 24498934, 2014). "It has been thought that a functional polymorphism in the promoter of the CD14 gene (CD14 −159C/T) is associated with H. pylori-related gastric carcinoma, ischemic heart disease, and atherosclerosis." (PMID 24228026, 2013). "In this study, we focus on normal healthy Korean population and aim to elucidate the association of risk factors for atherosclerosis and H. pylori infection according to the promotor polymorphism of the CD14 gene." (PMID 24228026, 2013). "In conclusion, the promoter polymorphism at −159C/T of the CD14 gene is positively associated with the risk factor of atherosclerosis in healthy Korean population." (PMID 24228026, 2013). "When the subjects were divided by gender, the risk of atherosclerosis according to CD14 polymorphisms was evaluated." (PMID 24228026, 2013). "We aim to elucidate the association of risk factors for atherosclerosis and H. pylori infection according to the promotor polymorphism of the CD14 gene in healthy Korean population." (PMID 24228026, 2013). "CD14, involved in two disease-related pathways, acts as an endotoxin receptor that mediates inflammatory signal transduction and is strongly associated with inflammatory mechanisms underlying atherosclerosis." (PMID 41283645, 2025). "In addition, CD14 has been linked to the development of atherosclerosis, because the extracellular vesicles secreted by monocytes that express this protein can induce endothelial damage in vitro (Aharon, Tamari & Brenner, 2008)." (PMID 35846887, 2022).